COCH (cochlin)
Diseases named in the same sentence as COCH in open-access papers (continued):
Sharing a sentence is not in itself a finding about the gene and the disease.
myopia (2 papers, 2023 to 2024). "The results of western blots validated the proteomic findings of cochlin upregulation in the myopic models and implicated the correlation of its abundancy with myopia severity." (PMID 37644183, 2023). "Taken together, the early initiation, phenotypic correlation, and stable maintenance of cochlin upregulation in myopia models validated the association of cochlin overexpression with myopia pathogenesis, implicating the role of cochlin as a molecular cue in the retina during myopigenesis." (PMID 37644183, 2023). "Utilizing high-throughput proteomics, a notable increase in the expression of cochlin is found in both guinea pig lens-induced myopia and form-deprived myopia models." (PMID 38725013, 2024). "The myopia-induced upregulation of cochlin expression in ocular posterior poles was validated by conventional approaches, including quantitative real-time PCR (qPCR), western blots, and immunohistochemistry (IHC)." (PMID 37644183, 2023). "Moreover, the 92% sequence homology between the human COCH gene and its guinea pig ortholog supports the preclinical study testing the efficacies of small hairpin RNAs against the human COCH gene in guinea pig myopia models." (PMID 37644183, 2023). "Then, cochlin, an ECM protein, with the most prominent upregulation in the myopia models, stood out." (PMID 37644183, 2023). "Due to the difficulty in obtaining ocular posterior pole tissues from subjects with nonpathologic myopia, the expression patterns of cochlin and SFRP-1, the 2 actionable targets identified in this study, have not been validated in clinical samples." (PMID 37644183, 2023). "Furthermore, genetic knockdown of the cochlin gene and pharmacological blockade of SFRP1 abrogates the reduced choroidal blood perfusion and prevents myopia progression in the FDM model." (PMID 37644183, 2023). "In addition, cochlin protein expression was also upregulated in the LIM model compared with normal controls, and its trend of expression paralleled the myopia severity among the experimental groups." (PMID 37644183, 2023). "Moreover, targeting cochlin and SFRP1 on this axis prevented myopia progression in the FDM model by improving choroidal circulation, indicating the potential of these molecules as interventional targets for myopia." (PMID 37644183, 2023). "The axis consisting of different signaling molecules, including cochlin, SFRP1, and CaMKII, and the corresponding tissue cell types, such as retinal photoreceptors, RPE cells, and choroidal vascular endothelial cells, was newly identified and proven to be responsible for myopia pathogenesis." (PMID 37644183, 2023). "Moreover, despite several lines of evidence in this study supporting the role of the cochlin/SFRP-1/CaMKII axis in the pathogenesis of nonpathologic myopia, the possibility that their overexpression may be the consequence of AL elongation cannot be excluded." (PMID 37644183, 2023). "A proteomics study using Guinea Pig ocular posterior pole tissues identifies a novel axis composed of cochlin in the retina, SFRP1 in the RPE, and CaMKII in choroidal vascular endothelial cells responsible for non-pathologic myopia." (PMID 37644183, 2023).
prostate carcinoma (2 papers, 2020). A carcinoma that arises from epithelial cells of the prostate gland. "A study shown that COCH was a transition zone-specific genes and was also stroma-specific of the prostate, and involved in the occurrence of prostatic hyperplasia and prostate cancer." (PMID 33281116, 2020).
Vertigo (2 papers, 2022 to 2023). An abnormal sensation of spinning while the body is actually stationary. "Consistent with Cochlin determining CaCO3 crystallization, Cochlin mutations in both human and mouse cause vestibular malfunction, while some human mutations also result in vertigo." (PMID 35958995, 2022). "COCH is the causal gene for DFNA9, characterized by a progressive high-frequency SNHL with variable progressive vestibular impairment; however, a family was reported in South Korea with episodic vertigo and bilateral SNHL with the mutation p.Cys162Tyr was considered a MD-like phenotype." (PMID 37022572, 2023).
Alzheimer disease (1 paper, 2024). A progressive, neurodegenerative disease characterized by loss of function and death of nerve cells in several areas of the brain leading to loss of cognitive function such as memory and language. "Additionally, SNPs inside COCH are associated with cortical thickness, changes in which, as ascertained through neuroimaging techniques, are commonly used in early detection and monitoring of Alzheimer’s disease progression." (PMID 39348415, 2024). "In the real data application to Alzheimer’s disease, we initially employed a traditional FDR cutoff of 0.05 and identified one significant gene, COCH, despite the constraints of a relatively small sample size consisting of 444 cases and 234 controls (totaling 678 individuals)." (PMID 39348415, 2024).
cocaine abuse (1 paper, 2012). Disorders related or resulting from use of cocaine. "For the treatment of cocaine abuse, one would expect that a CocH or CocE can be used to build a strong defense system through rapidly degrading cocaine in plasma so that the cocaine molecules are prevented from entering the brain." (PMID 22844238, 2012). "For development of a CocH-based therapy for cocaine abuse, it is essential to know whether a cocaine-metabolizing enzyme can effectively prevent cocaine from entering brain and producing physiological effects." (PMID 22844238, 2012).
colon cancer (1 paper, 2024). "Ultimately, specific methylation markers (PCDH20, APCDD1, and COCH) were identified as effective markers for identifying cluster that would benefit from immunotherapy in colon cancers." (PMID 38327746, 2024). "Furthermore, we found beneficial-cluster of specific methylation markers (PCDH20, APCDD1, COCH) that could be used in conjunction with microsatellite status to expand the pool of colon cancer patients eligible for immunotherapy." (PMID 38327746, 2024).
conductive hearing loss (1 paper, 2021). "In addition, future clinical studies should evaluate for potential presence of conductive hearing loss in patients with COCH pathogenic variants." (PMID 34108864, 2021).
HCMV infection (1 paper, 2024). "Finally, we also noted that COCH transcripts, encoding the cochlin protein, were significantly upregulated by HCMV infection." (PMID 38440980, 2024).
hearing (1 paper, 2019). "Family segregation was concordant, as her sister presented only hearing loss, associated with the COCH pathogenic variant." (PMID 31393079, 2019).
liver fibrosis (1 paper, 2025). "ECM remodeling is essential in liver fibrosis, and the upregulation of actin cytoskeleton-associated genes (COCH and ACTB) denotes increased ECM deposition and cellular motility, which are characteristics of liver fibrosis and HCC progression." (PMID 40901642, 2025).
neurofibromatosis type 2 (1 paper, 2021). "One was diagnosed with neurofibromatosis type 2 and the other displayed a variant in the COCH gene." (PMID 34440452, 2021).
nonsyndromic hearing loss (1 paper, 2014). "Of the 23 probands, six had mutations in DFNA genes [WFS1 (n = 2), COCH, ACTG1, TMC1, and POU4F3] known to cause autosomal dominant nonsyndromic hearing loss." (PMID 25388789, 2014).
osteoporosis (1 paper, 2023). A condition of reduced bone mass, with decreased cortical thickness and a decrease in the number and size of the trabeculae of cancellous bone (but normal chemical composition), resulting in increased fracture incidence. "KCNMA1-AS1/miR-1303/cochlin (COCH) axis was identified as a novel biomarker and therapeutic target for osteoporosis." (PMID 36717952, 2023). "Our findings suggest that the KCNMA1-AS1/miR-1303/COCH axis is a promising biomarker and therapeutic target for osteoporosis." (PMID 36717952, 2023). "Further animal experiments are needed to certify the feasibility of the KCNMA1-AS1/miR-1303/COCH axis as a potential therapeutic target for osteoporosis." (PMID 36717952, 2023). "And we provided 2 osteoporosis-related mRNAs with ceRNA activity (COCH, RARG) as promising candidate downstream mRNAs of miR-1303." (PMID 36717952, 2023). "In conclusion, we showed that miR-1303 was downregulated, while KCNMA1-AS1 and COCH were upregulated in osteoporosis subjects." (PMID 36717952, 2023). "Summarily, our findings suggest that the KCNMA1-AS1/miR-1303/COCH axis is a promising biomarker and therapeutic target for the diagnosis and treatment of osteoporosis." (PMID 36717952, 2023). "miR-1303 was lowly expressed, while cochlin (COCH) and KCNMA1-AS1 were highly expressed in the osteoporosis subjects." (PMID 36717952, 2023). "Surprisingly, qRT-PCR showed that the elevation of RARG in the osteoporosis subjects was not significant, while the mRNA level of COCH was increased significantly." (PMID 36717952, 2023). "However, by performing qRT-PCR, we found that COCH was increased significantly while RARG showed a mild elevation without statistic difference in the osteoporosis subjects compared to the control subjects." (PMID 36717952, 2023).
progressive sensorineural hearing loss (1 paper, 2022). "Pathogenic missense variants in COCH are associated with DFNA9, an autosomal dominantly inherited type of progressive sensorineural hearing loss with or without vestibular dysfunction." (PMID 35204720, 2022).
Tinnitus (1 paper, 2020). Tinnitus is an auditory perception that can be described as the experience of sound, in the ear or in the head, in the absence of external acoustic stimulation. "An association between tinnitus and COCH gene mutation has been reported in the analysis of a family with the mutation." (PMID 32747715, 2020). "They identified a heterozygous 18 base pair deletion on exon 11 of the COCH gene in a large multigenerational family, segregating late-onset progressive bilateral sensorineural hearing impairment and tinnitus." (PMID 32747715, 2020).
Usher syndrome type 1 (1 paper, 2014). A syndrome characterized by congenital, bilateral, severe sensorineural hearing loss, abnormalities in the vestibular system, and adolescent-onset retinitis pigmentosa. "In particular, from the prognostic perspective, we can expect successful results of CI in hereditary deafness with mutation of specific genes, such as, GJB2, SLC26A4, mitochondrial mutations, OTOF, Usher syndrome type I, DFNA9 (COCH), and DFNA17 (MYH9)." (PMID 25373420, 2014).
tumor (6 papers, 2020 to 2025). "Conversely, upregulation of E2F targets (e.g., PRDX4, MCM2; FDR = 2.6e-24) and extracellular matrix genes (e.g., COCH, MATN3; FDR = 8.0e-18) were strongly associated with tumor growth and resistance to ICI-4W." (PMID 37433281, 2023). "We speculate that COCH overexpression may induce the secretion of multiple cytokines and enhance the recruitment of immune cells, leading to the imbalance of the local inflammatory environment of TME and mediating the immune escape of tumor cells." (PMID 33281116, 2020). "In the HPA data, compared with normal tissues, the expression of PKMYT1, ETF1, RECQL4, TUBB2B, and CDC6 in tumor tissues was remarkably upregulated, while the expression of TFRC and PITX1 was significantly downregulated (,ECT2, BUBB1B, and COCH were not included)." (PMID 33869220, 2021). "According to the CPTAC data, the protein expression of PKMYT1, ETF1, ECT2, BUB1B, and RECQL4 in tumor tissues was significantly increased, while the expression of TFRC was significantly reduced, and the expression of COCH and TUBB2B did not change significantly (PITX1 and CDC6 were not included)." (PMID 33869220, 2021).
bacterial infection (4 papers, 2020 to 2021). "Previous studies have demonstrated that cochlin plays a role in coordinating immune responses elicited by bacterial infection of the cochlea." (PMID 34768980, 2021). "The exact function of cochlin is not fully understood but previous studies indicated that cochlin is involved in the clearance of bacterial infections in the inner ear where the LCCL domain is cleaved by aggrecanase-1 and secreted into the scala tympani." (PMID 34768980, 2021). "A recent study demonstrated that Coch−/− mice have a significantly decreased immune response after a bacterial infection in the inner ear as functional cochlin is necessary to induce an innate immune response." (PMID 34768980, 2021). "Similar to the spleen, the LCCL of cochlea-derived cochlin is cleaved and secreted into the scala tympani to promote an immune response against bacterial infection via pathogen segregation." (PMID 33193034, 2020). "It has been reported that cochlin in the spleen promotes the systemic innate immune reaction against bacterial infection." (PMID 33193034, 2020). "Furthermore, cochlin LCCL is diminished in RDEB (col7‐deficient) mice and patients during bacterial infections." (PMID 34142388, 2021). "Besides a role in the clearance of bacterial infections in the inner ear, cochlin has a function in maintaining the structure of the ECM of the inner ear by the affinity of the vWFA domains for type I, type II and type IV collagens." (PMID 34768980, 2021). "Similar, Cochlin, secreted from follicular dendritic cells in the spleen, was crucial for systemic immune response against bacterial infection by induces secretion of cytokines (IL-1βand IL-6) and enhances the recruitment of immune cells (neutrophils and macrophages)." (PMID 33281116, 2020). "The enzyme aggrecanase cleaves cochlin in response to bacterial infection, releasing the cochlin LCCL domain into the bloodstream, and the cochlin LCCL domain activates macrophages." (PMID 34142388, 2021).
cancer (3 papers, 2022 to 2024). A tumor composed of atypical neoplastic, often pleomorphic cells that invade other tissues. "In this study, the use of GAG-modified cells and cancer cells revealed that cochlin is a useful probe for flow cytometry, lectin staining of cells or tissue slices, pull-down assay, and lectin blotting." (PMID 36511224, 2023). "The other four genes, COCH, CST9, SOX11, and TDGF1, as well as CHST4, have also been implicated in the immune-related GO term, indicating the importance of immunomodulatory mechanisms in cancer therapy." (PMID 38396947, 2024).
genetic disorder (2 papers, 2016 to 2024). "Regarding genetic disorders, a definite diagnosis with a genetically confirmed mutation in the COCH gene was most prevalent (N = 15)." (PMID 26973594, 2016). "Regarding genetic disorders, most patients presented with a mutation in their COCH gene." (PMID 26973594, 2016). "Therefore, BVH patients suspected of a genetic disorder (based on clinical manifestation and family history) other than a confirmed COCH gene mutation, were classified as having a genetic disorder as the probable cause of BVH." (PMID 26973594, 2016).
infection (2 papers, 2020 to 2021). The state of being infected such as from the introduction of a foreign agent such as serum, vaccine, antigenic substance or organism. "COCH, enriched in the biological process of regulating innate immune response positively, is the first line of defense against infection through activating and increasing the frequency, rate, and extent of the innate immune response." (PMID 34965257, 2021).
COCH also shares sentences with these, for which no sentence is quoted: Hearing impairment (5 papers); herpes infection (3); Lyme disease (3); meningitis (3); autoimmune disease (2); neuritis (2); auditory neuropathy spectrum disorder (1); Axenfeld-Rieger syndrome type 3 (1); bladder cancer (1); cholesteatoma (1); connective tissue disorder (1); dementia (1); embryonal carcinoma (1); Hashimoto thyroiditis (1); lattice corneal dystrophy (1); malaria (1); migraine (1); myocarditis (1); neuropathy (1); non-small cell lung carcinoma (1); Onset (1); osteosarcoma (1); presbycusis (1); Primary open-angle glaucoma (1); prostatic hyperplasia (1); renal carcinoma (1); renal cell carcinoma (1); renal failure (1); Stroke (1); sudden deafness (1).